KRT19 (keratin 19)
Diseases named in the same sentence as KRT19 in open-access papers (continued):
Sharing a sentence is not in itself a finding about the gene and the disease.
tumor (continued). "The PDx grown in SCID mice showed strong staining of human cytokeratin 19 and Ki-67, demonstrating the growth of the tumor." (PMID 32235707, 2020). "First, they proved that OVA expressed on tumor metaplasia and colocalized with pancreatic ductal cell marker cytokeratin 19+ (CK19)." (PMID 32616713, 2020). "Tumour cells in pDKO/R pancreata expressed the ductal cell marker cytokeratin 19 (CK19) and mucin, characterising the observed tumours as PDAC." (PMID 32641778, 2020). "Immunohistochemical staining of cytokeratin 19 (CK-19) revealed a dramatic increase in tumor nodules, followed by tumor progression, in the KrasLA2 control group." (PMID 32481524, 2020). "Cytokeratin-19 (CK19) expression was correlated with metastasis, early tumor reappearance after resection, and radiofrequency ablation." (PMID 30774659, 2019). "In line with the proposed signaling functions, we recently demonstrated that KLK4, in combination with KLK5, 6, and 7, regulates gene expression of other tumor-relevant genes such as MSN (encoding moesin), KRT7 and KRT19 (encoding keratins 7 and 19)." (PMID 30811511, 2019). "Growing evidence indicates that the tumor biomarker cytokeratin 19 fragment (CYFRA21-1) is significant for a variety of cancers." (PMID 31767040, 2019). "We examined KRT19 expression by IHC in all primary tumours of the study and 9 samples of patients with granulomatous diseases." (PMID 31331335, 2019). "Their blood data including albumin and C-reactive protein for Glasgow Prognostic Score and cytokeratin 19 fragment 21-1 as a tumor marker were measured before starting treatment." (PMID 31038863, 2019). "Univariate and multivariate analysis revealed that AFP, tumor diameter, vascular invasion and cytokeratin-19/glypican-3 sub-typing were independent prognostic factors for RFS, thus comprised the risk scoring model." (PMID 31676847, 2019). "Univariate analysis revealed that BMs were associated with clinical stage, smoking history, tumor histologic type, carcinoembryonic antigen (CEA) level, cytokeratin 19 fragment (CYFRA) 21-1 level, and cancer antigen (CA) 125 level." (PMID 30536037, 2019). "Although Keratin 19 (KRT19) has been reported as a tumor cell marker and found to interact with other proteins that modulate cancer properties, its role in cancer prognosis remains to be fully elucidated." (PMID 30650643, 2019). "CYFRA 21-1 is a soluble fragment of cytokeratin 19 and tumours arising within the anal canal are most often keratinizing tumours, suggesting the possible value of this marker in ASCC." (PMID 29653564, 2018). "The staining for KRT19 was present in all tumor samples, with strong staining in 20 to 80% of the cells." (PMID 30550540, 2018). "Some conventional tumor markers in MPE such as carcinoembryonic antigen (CEA), carbohydrate antigen (CA) -153 and cytokeratin 19 fragment (CYFRA 21-1) appear to show a certain diagnostic value." (PMID 30522463, 2018). "Although KRT19 is one of the most frequently used marker for tumor cell detection, recent results showed, that KRT19 is a potential tumor suppressor." (PMID 30021014, 2018). "Strong staining of KRT19 was localized to the peripheral, less differentiated areas of the tumor nests." (PMID 30550540, 2018). "LNs from colectomies with and without preoperative endoscopic tattooing were assessed by two methods, hematoxylin and eosin (HE), and RT-LAMP, to detect tumor cytokeratin 19 (CK19) mRNA." (PMID 27324339, 2017). "Higher levels of cytokeratin 19 (CK19) in lymph nodes was positively correlated with tumor size in stage I and II CRC patients." (PMID 29090038, 2017). "Studies assessing the EMT profile in 20 ascites- and 6 tumor-primary cultures derived from patients diagnosed with advanced-stage high-grade serous OC, showed the expression of E- and N-cadherin, cytokeratin 19 and vimentin mRNA in all samples." (PMID 28934230, 2017).
tumor (continued). "The expression level of CTLA4 only correlated with central tendency parameters, while expression of GLUL, FGFR4, tumour stemness markers KRT19 and EPCAM and immune checkpoint PDCD1 showed significant correlations with MRI heterogeneity parameters only." (PMID 28550313, 2017). "High level of human cytokeratin 19 was found in the tumor sections in nickel-treated group compared with that of control group." (PMID 29127306, 2017). "To further document the correlation between miR-26a and KRT19, we divided the CCA patients into two subgroups (KRT19high and KRT19low) by using the medium of KRT19 expression in tumor tissues as cutoff." (PMID 27833076, 2016). "We determined the frequency and extent of cytokeratin 19 (CK19) expression in OSCC primary tumours and surrounding tissues to explore the feasibility of a “clinic-ready” intraoperative diagnostic test (one step nucleic acid amplification—OSNA, sysmex)." (PMID 27393570, 2016). "Secondary endpoints included surgical bleeding, plasma levels of vWF, and circulating tumor cells (CTCs) as measured by quantitative PCR of cytokeratin-19 transcripts." (PMID 26306290, 2015). "Cytokeratin 19 (CK-19) is an intermediate filament protein that is critical to epithelial cell structural integrity and used as a highly sensitive biomarker for tumor cell dissemination in the lymph nodes, bone marrow, and peripheral blood." (PMID 26588210, 2015). "CYFRA 21–1 (cytokeratin 19) has been proposed as an independent and sensitive tumor marker for NSCLC since 1993." (PMID 25880432, 2015). "Keratin-31, vimentin, prohibitin, etc., were up-regulated in tumour stroma; Rho GDP dissociation inhibitor (GDI) β, superoxide dismutase, keratin-19, and annexin-A2 were down-regulated in tumour stroma." (PMID 26184160, 2015). "Historically, it was believed that BCCs arise from the lower PSU owing to the morphological resemblance of the tumour cells to hair follicles and the expression of hair follicle markers such as Krt17 and Krt19 in tumour tissues." (PMID 24961797, 2014). "KRT19 was reported as a biomarker for tumor growth or metastasis in HCC;17 however, the detailed pathway involved by the abnormal expression of KRT19 still remained unclear." (PMID 25476897, 2014). "Both Linc00974 and KRT19 expression significantly correlated with decreased tumor differentiation grade (P<0.001), increased tumor size (P<0.001), and metastasis (P<0.001)." (PMID 25476897, 2014). "In PB samples, KRT19 mRNA played a predominant role in identifying potential circulating tumor cells." (PMID 23671585, 2013). "The GeneSearch BLNA assay (Veridex LLC, WARREN, NJ, USA) is a now discontinued commercial intra-operative qPCR assay that detected the presence of tumour-specific markers cytokeratin-19 (CK-19) and mammaglobin (MGB) in sentinel lymph nodes." (PMID 23797656, 2013). "The tumor showed diffusely positive reactivity with cytokeratin (Pan), cytokeratin 19, cytokeratin 5/6, cytokeratin 7, EMA, vimentin, CD56, and NSE and also showed variable reactivity with glial fibrillary acidic protein (GFAP) and VEGF." (PMID 22472343, 2012). "This tumor we report was positive for cytokeratin (Pan), cytokeratin 19, cytokeratin 5/6, cytokeratin 7, and epithelial membrane antigen, so it is easy to differentiate them by immunohistochemistry." (PMID 22472343, 2012). "From this set, we then selected three of the hypermethylated genes, Kruppel-like transcription factor 11 (KLF11), deleted in lung and esophageal cancer 1 (DLEC1), keratin 19 (KRT19) for further analysis based on their known tumor suppressor functions." (PMID 22428009, 2012). "Keratin 19 positive tumours had significantly more distant metastasis (stage 2) and showed a poorly differentiated histology (grade 3) in comparison with K19 negative tumours (P = 0.001 and 0.0002 respectively)." (PMID 20167095, 2010). "Keratin 19 expression in 30-90% of the tumour cells was seen in four of the 34 hepatocellular tumours (12%)." (PMID 20167095, 2010).
tumor (continued). "Keratin 19 positive tumours histologically had irregular growth patterns and were poorly differentiated." (PMID 20167095, 2010). "Weak expression of keratin 19 was detected in the PE14 mouse tumours, but this has also been reported to be a marker for the cancer stem cell." (PMID 18541018, 2008). "HER2/neu overexpression was identified by immunohistochemistry, whereas cytokeratin 19 (CK-19) mRNA-positive circulating tumor cells (CTCs) in the peripheral blood were identified by real-time PCR." (PMID 16846533, 2006). "For instance, cytokeratin 19 (CK 19) transcripts were used in several studies as a molecular marker for tumour cell detection." (PMID 16091757, 2005). "Consistent with our previous findings, all the acinar-derived tumor cells were associated with strong expression of KRT19, a marker of normal ductal lineage not expressed in healthy acinar cells." (PMID 41480763, 2026). "In vivo, KRT19-overexpression increased peritoneal tumour burden." (PMID 41714116, 2026). "Compared with SDNs of p-LUAD, p-LUSC demonstrated elevated positivity for CYFRA 21-1, which was a soluble cytokeratin 19 fragment expressed in bronchial epithelium and related malignancies, released during cell degradation, and thus represents a useful serum tumor marker." (PMID 41590367, 2026). "To further evaluate the vascular integrity in PAK4KO tumours, we employed multiplex immunofluorescence to assess the VE-cadherin expression as a marker of the vascular integrity in tumour tissues We used cytokeratin 19 as a tumour cell marker and CD31 as an endothelial cell marker." (PMID 41294859, 2025). "Thus, we deeply explored the role of KRT19 on PTC function based on public databases and demonstrated that high expression of KRT19 in PTC promotes tumor growth and metastasis." (PMID 39453570, 2025). "In recent years, with the advancement of molecular pathology and tumor microenvironment research, biomarkers such as cytokeratin 19 (CK19), Ki67 antigen (Ki67), and β-catenin have gradually become key targets for analyzing HCC heterogeneity, invasiveness, and recurrence risk." (PMID 41388520, 2025). "tsRNA-49-73-Glu-CTC is highly expressed in the serum of patients with NSCLC and demonstrates superior diagnostic value compared to commonly used tumor markers in clinical practice, such as Carcinoembryonic Antigen (CEA), Neuron-Specific Enolase (NSE), and Cytokeratin 19 Fragment (CYFRA)." (PMID 40153423, 2025). "In our cohorts, significant enrichment of the genes involved in the keratinization and the formation of keratinized layers in tumor tissue (KRT5, KRT6A-C, KRT13-KRT17, KRT19) and genes associated with the regulation of cell division (FOXM1, p63) was identified." (PMID 38398111, 2024). "S-III tumours exhibit more aggressive characteristics including the upregulation of proteins associated with a poor prognosis (such as TGFβ1, KRT19 and MMP9) and the activation of tumour-promotion pathways (such as TGFβ, HIF1, integrin and Rho GTPases pathways)." (PMID 39261716, 2024). "The tumor cells of int-CAs showed coexpression of hepatocytic (HepPar1, arginase-1, or α-fetoprotein) and biliary markers (cytokeratin 19 or carcinoembryonic antigen), and at least 1 of the hepatocyte markers and 1 of the biliary markers were detected by immunohistochemical stain." (PMID 39101773, 2024). "Additionally, calculation of tumour‐related epithelial markers (EPCAM, KRT8 and KRT19) for each spot in all samples revealed that tumour areas showed the highest epithelial scores compared to other areas, confirming the accurate identification of tumour areas." (PMID 39187937, 2024). "EPCAM and cytokeratin 19 were reported as progenitor and tumor stem cell markers in HCC." (PMID 38773585, 2024).
tumor (continued). "Taken together, these studies reaffirm our bioinformatics-based analysis and suggest that these extracellular matrix genes (CDH3, COL11A1, COL1A1, COL17A1, KRT19, ITGA2, LAMC2, and SULF1) are highly associated with PDAC tumor carcinogenesis and peritoneal metastasis." (PMID 39682235, 2024). "The combination of plasma TP73‐AS1, CRNDE, and two classical tumor markers, carcinoembryonic antigen (CEA) and cytokeratin 19 fragment (CYFRA21‐1), showed excellent diagnostic performance for NSCLC (AUC =0.927 in the training set; AUC = 0.925 in the testing set)." (PMID 35871358, 2023). "We also found LAMC2, KRT8 and KRT19 spatially patterned tumor markers sharing ‘epidermis development’ and ‘cellular component morphogenesis’ spatially patterned pathways in the tumor region, which may indicate the proliferation of cancer cells." (PMID 36243975, 2023). "Interestingly, contrary to the transcriptomic findings, KRT5 and KRT19 were coexpressed in most tumour cells and normal basal epithelial cells in IMC images, except for a subset of KRT5–/KRT19+ tumour cells in P04." (PMID 37349991, 2023). "Higher expression of EpCam and KRT19 in tumor tissues confirmed that they were malignant." (PMID 36865791, 2023). "KRT19 represents one of the factors determining tumor response to chemo/radiotherapy." (PMID 36949761, 2023). "Notably, the cytokeratin 19 (CK19)+ tumor compartment was also reduced in the transplants with HDAC-deficient CAFs, largely proportionally to the α-SMA+ fibroblast compartment, indicating lower tumor-promoting effect from HDAC-deficient CAFs." (PMID 38057326, 2023). "After excluding potential low‐quality cells and removing a cluster with high expression of epithelial markers (such as EPCAM, KRT8, KRT19) to distinguish fibroblasts from tumour cells undergoing epithelial‐mesenchymal transition (EMT), 13 subclusters of fibroblasts were retained." (PMID 38115703, 2023). "Most of these cells were tumor epithelial cells, characterized by high expression of keratin 19 (KRT19) and low expression of PTPRC (CD45), PECAM1 (CD31), and PDGFRB, which are markers for immune/hematopoietic cells, endothelial cells, and stromal cells, respectively." (PMID 37966117, 2023). "The subtypes were also associated with tumor biomarkers such as NSE, KRT19, and CA125." (PMID 36357897, 2022). "Besides the differential expression of KRT5 and KRT19 between the margin and tumor center, KRT6B, KRT8, KRT10, and KRT17 were identified among the proteins differentiating the cancer from control tissue." (PMID 35512017, 2022). "Although the expression of cytokeratin 19 should just represent tumor cells as cell type-specific epithelial markers, we found correlations with Gleason scores in the whole cohort (Pearson’s R = −0.35, p = 0.02) and with the TNM score in the ADT+ group (Pearson’s R = −0.78, p = 0.008)." (PMID 36077632, 2022). "It was exciting that the AUC was as high as 0.852, suggesting that KRT19 might be used as a tumor marker for the diagnosis of BRCA." (PMID 36292723, 2022). "Intriguinly, expression of KRT19 was strongly correlated with the tumor T stage." (PMID 33442422, 2021). "In addition, it was found that KRT19 correlated with tumor size, tumor differentiation, metastasis and micovascular invasion of HCC." (PMID 33442422, 2021). "In addition, KRTs and notably KRT7, KRT18 and KRT19, are widely used to detect circulating tumor cells in the blood or detached tumor cells in ascites." (PMID 34070214, 2021). "By contrast, the tumor marker cytokeratin 19 was markedly more expressed in 4T1 than in CAFs." (PMID 33562504, 2021).
tumor (continued). "The critical factor on the basis of this opposing regulation is whether KRT19 could bind to RAC1 in the cytoplasm of tumor cells." (PMID 33767587, 2021). "In contrast, cytokeratin 19 fragments (CYFRA 21-1) are classical tumor-associated antigens that are mainly expressed in lung tissue and released from advanced cancers as a reflection of high tumor activity or large tumor mass." (PMID 33672622, 2021). "Similarly, regions with strong HA-tag expression in the PDAC tumor graft also expressed less KRT19 and KRT7 and substantially higher levels of mesenchymal markers such as N-CAD (pound sign)." (PMID 34680288, 2021). "We speculated that interaction between KRT19 and other proteins including cell proliferatin marker Ki-67, initiated signaling cascades that promoted tumorigenesis, tumor invasion and metastasis." (PMID 33442422, 2021). "In addition, HMGB1 was compared with established tumor markers cytokeratin 19-fragments (CYFRA 21-1), carcinoembryonic antigen (CEA) and neuron specific enolase (NSE)." (PMID 33672622, 2021). "Thus, in our transcriptomic profiling of the stroma, KRT19 overexpression was certainly related to adjacent tumour epithelial cells." (PMID 32376891, 2020). "Furthermore, serum tumor markers of cytokeratin 19 fragment (CYFRA21-1), carcino-embryonic antigen (CEA) and neuron specific enolase (NSE) in most patients increased obviously." (PMID 32587276, 2020). "Traditional tumor-associated antigens such as carcinoembryonic antigen (CEA), neuron-specific enolase (NSE), and cytokeratin 19 fragment 21-1 (Cyfra21-1) play poor roles in early detection of lung cancer because the sensitivity and specificity are not satisfied." (PMID 32596148, 2020). "Thus, we examined the role of KRT19 in regulating cancer progression as an oncogene or tumor suppressor gene." (PMID 30650643, 2019). "However, both tumour types have an over 96% expression of KRT19, a commonly used marker for epithelial tumours." (PMID 31331335, 2019). "We also examined keratin 19 expression of different histological types lung primary tumours." (PMID 31331335, 2019). "Interestingly, OATP5A1 was more frequently detectable in tumor cells with weaker cytokeratin-19 staining compared with that in cells with strong cytokeratin-19 staining." (PMID 30131693, 2018). "In order to translate these in vitro findings to the bedside, E-cadherin, N-cadherin, cytokeratin 19 and vimentin mRNA expression levels were evaluated in 6 tumor- and 20 ascites-primary cultures derived from patients diagnosed with advanced-stage high-grade serous OC." (PMID 28934230, 2017). "Molecular detection of tumor cytokeratin 19 (CK19) mRNA with RT-LAMP was performed in 3206 LNs from 188 CC patients using two methods: individual analysis of 1449 LNs from 102 patients (individual cohort), and pooled LN analysis of 1757 LNs from 86 patients (pooling cohort)." (PMID 28088238, 2017). "In addition, the expression levels of 4 EMT-markers (E-cadherin, N-cadherin, cytokeratin 19 and vimentin) were evaluated in human OC ascites- and tumor-primary cultures." (PMID 28934230, 2017). "Labeling for cytokeratin 19 (CK19) demonstrated VM structures were formed by dense tumor cells." (PMID 25895023, 2015). "For example, a Linc00974 antagonist might be developed for targeting upregulation of KRT19, which may be involved in tumor growth and metastasis." (PMID 25476897, 2014). "We also detected the expression level of KRT19 in tumor samples obtained above." (PMID 25476897, 2014). "In conclusion, the combination of Linc00974 and KRT19 may be novel indices for clinical diagnosis of tumor growth and metastasis in HCC, while Linc00974 may become a potential therapeutic target for the prevention of HCC progression." (PMID 25476897, 2014). "Omission of axillary lymph node dissection could be proposed in patients presenting a sentinel lymph node with a cytokeratin 19 mRNA copy number <2000 and a Luminal tumor phenotype." (PMID 23533593, 2013).